RACK1 (receptor for activated C kinase 1)
Diseases named in the same sentence as RACK1 in open-access papers (continued):
Sharing a sentence is not in itself a finding about the gene and the disease.
cancer (continued). "RACK1 also brings FAK and PDE4D5 together which strongly suggests that adhesion signaling and cAMP signaling are linked in cancer." (PMID 21978545, 2011). "To this end, we determined RACK1 expression in various cancers and in healthy tissues by immunohistochemistry." (PMID 21935400, 2011). "As well as this, RACK1 scaffolds a host of other different kinases and phosphatases, and the activity of several of these proteins is altered in cancer." (PMID 21978545, 2011). "Since increased fatty acid levels provide essential building blocks for cancer growth, we investigated whether RACK1‐mediated lipid synthesis plays a role in CC growth." (PMID 39425259, 2025). "Dysregulation of RACK1 expression influences tumorigenesis, potentially promoting proliferation, metastasis, invasion, and chemoresistance in various cancers, including ovarian, breast, lung, osteosarcoma, hepatocellular, cervical, and oral squamous cell carcinoma." (PMID 39891099, 2025). "Additionally, some cancer cells exhibit reduced expression of the E3 ligase responsible for RACK1 ubiquitination, correlating with elevated RACK1 protein levels." (PMID 41373878, 2025). "This suggests that RACK1 may have potential anti‐cancer effects through the regulation of cancer metabolism." (PMID 39425259, 2025). "Moreover, they can affect tumor growth by targeting protein Receptor for Activated C Kinase 1 (RACK1), which is the bridge between cancer progression and the immune system." (PMID 39415794, 2024). "This duality makes RACK1 a powerful key to unlocking more effective cancer treatments." (PMID 39458945, 2024). "Specifically, SBSGL impedes HB tumour growth by inhibiting the O‐GlcNAcylation of RACK1, which is involved in multiple signalling pathways, affecting processes such as cell growth and migration and is aberrantly expressed in a wide range of malignant tumours." (PMID 38451046, 2024). "The E3 ligase RAB40C ubiquitinates and destabilizes RACK1 to promote cancer cell proliferation." (PMID 38315284, 2024). "Our study showed that silencing RACK1 reduced the effectiveness of the H9 antibody in these cancer cells, suggesting that targeting RACK1 with H9 could be a promising strategy for cancer treatment." (PMID 39458945, 2024). "RACK1 exacerbates cancer via activating multiple proto-tumoral processes in other solid tumors." (PMID 38315284, 2024). "PubMed, Embase, Web of Science, Cochrane Library, and Scopus were comprehensively explored from their inception to April 20, 2023, for selecting studies on the clinicopathological and prognostic role of RACK1 in patients with cancer that met the criteria for inclusion in this review." (PMID 37601269, 2023). "RACK1 may be a global predictive marker of poor prognosis in patients with cancer and unfavorable clinicopathological characteristics." (PMID 37601269, 2023). "No publication bias was observed in the association between RACK1 expression and lymphatic invasion (Begg’s test: P = 0.692; Egger’s test: P = 0.258) of cancer." (PMID 37601269, 2023). "RACK1 has emerged as a potential prognostic marker and drug target in numerous cancers." (PMID 37828084, 2023). "In this study, thirteen studies investigating 2,620 patients with cancer were included to assess the relationship between RACK1 expression and OS, and the pooled HR indicated that higher RACK1 expression might predict poorer OS." (PMID 37601269, 2023). "However, its expression did not correlate with lymphatic invasion in CRC and PC in our study; therefore, more well-designed studies are required to ascertain the role of RACK1 in various cancers." (PMID 37601269, 2023). "However, the exact function of RACK1 in cancer cellular processes, especially in proliferation, remains controversial." (PMID 37848434, 2023). "The mechanism whereby RACK1 regulates cancer progression remains to be elucidated." (PMID 37848434, 2023).
cancer (continued). "Taken together, these results suggest that the function of RACK1 in cancer progression may be diverse and dependent on tissue type and context." (PMID 37848434, 2023). "The function of RACK1 in tumorigenesis is cancer-type specific." (PMID 33537079, 2021). "Thus, RACK1 is considered to be a crucial factor affecting the development and progression of cancer." (PMID 33537079, 2021). "RACK1 acts as a versatile hub in cancer by shuttling proteins around the cell, anchoring proteins at particular locations, and stabilizing protein activity through interactions with the ribosomal machinery, several cell surface receptors, and proteins in the nucleus." (PMID 34039363, 2021). "As the irreversible loss of proliferation characterizes senescence and apoptosis, high RACK1 expression may be involved in the pathogenesis of many cancers." (PMID 34837888, 2021). "Receptor for activated C kinase (RACK1) belongs to the WD repeat family of proteins and functions as a scaffold protein to regulate multiple cellular processes, including translation, immunity, apoptosis, and cancer progression." (PMID 33983927, 2021). "In this context, the signalling hub protein RACK1 (Receptor for Activated C Kinase 1) could represent a nexus between cancer and the immune system due to its roles in cancer progression and innate immune activation." (PMID 33287384, 2020). "Nowadays, RACK1 is known to be involved not only in the immune response but also acts as a signalling hub, facilitating the cross-talk between several pathways involved in various biological events such as neuronal activity and cancer progression." (PMID 33287384, 2020). "RACK1 has been confirmed to take part in multiple biological events, including cell migration, virus infection, neural development, angiogenesis and cancer metastasis." (PMID 31997535, 2020). "Elevations in O-GlcNAcylation are associated with increased NLRP3 inflammasome and NF-κB signalling activity, with the NLRP3 inflammasome important to cancer progression and tumour microenvironment regulation, with effects at least partly regulated by the O-GlcNAcylation of RACK1." (PMID 33375613, 2020). "In recent years, RACK1 has been reported as an oncogene in many human cancers." (PMID 31949482, 2020). "CIRBP is known as a mediator of cancer-related inflammation and has been reported to act both as a tumour suppressor and a tumour promoter, depending on the cell type and cancer stage, while RACK1 plays an important role in the regulation of key signalling pathways in cancer." (PMID 31443305, 2019). "In addition, RACK1 protein is reported to mediate diverse signaling pathways both in plants and in human like drought, salt stress in crops and cancer metastasis in human." (PMID 31143369, 2019). "The function of Rack1 on cancer progression is cancer type-specific." (PMID 31113450, 2019). "Next, we analyzed the effects of RACK1 levels on clone cancer cell proliferation and apoptosis." (PMID 30451832, 2018). "It has been reported that RACK1 activates JNK-signaling pathway in the cancer cells." (PMID 30451832, 2018). "Previous studies indicate that RACK1 is an autophagy inducer in physiology, but the role of RACK1 in the autophagy of cancer cells is unknown." (PMID 30451832, 2018). "Additionally, expression of RACK1 is an excellent predictor of poor clinical outcome in OSCC as well as other common cancers." (PMID 30460084, 2018). "Although these studies indicate RACK1 as an autophagy inducer in physiology, the role of RACK1 in the regulation of cancer cell autophagy remains unknown." (PMID 30451832, 2018). "Previous studies suggest that RACK1 is an autophagy inducer in physiology, but the role of RACK1 in the autophagy of cancer cells is unknown." (PMID 30451832, 2018). "More recently, the EMT process had been described as crucial for cancer metastasis progression in which RACK1 could participate." (PMID 27763568, 2016).
cancer (continued). "These conflicting reports suggest that the biological effect of Rack1 on cancer progression may be cell-type and context specific." (PMID 27754360, 2016). "Abnormal expression of Rack1 was observed in many types of cancer." (PMID 27754360, 2016). "However, the detailed function of Rack1 in cancer cell proliferation and invasiveness remains undefined because of conflicting reports." (PMID 27754360, 2016). "In other words, the functional diversity of Rack1 in cancer might depend on the properties of its binding proteins." (PMID 27754360, 2016). "Emerging studies show that dysregulated RACK1 is supposed to be a biomarker or regulator in a wide spectrum of human cancers, which implies that RACK1 could play an important role in genesis and progression as well as resistance to chemotherapy in tumors." (PMID 27763568, 2016). "Aberrant expression of Rack1 is observed in many types of carcinoma." (PMID 27754360, 2016). "Although the mechanism underlying the involvement of NHE9 in tumors was unclear, previous studies established an important role for RACK1 in cancer cell apoptosis, which led us to investigate the possibility that NHE9 induced CRT resistance by affecting the RACK1-associated apoptosis pathway." (PMID 25915159, 2015). "In addition, over-expression of RACK1 has been reported to be strongly related to poor clinical outcomes of many carcinomas." (PMID 25686824, 2015). "Thus, RACK1 interacts with Src and Fyn respectively in cultured cancer cells and in neurons, and this interaction inhibits the activity of the kinases, suggesting that RACK1 plays an inhibitory role on Src and Fyn kinase's function." (PMID 21978545, 2011). "There are several mechanisms by which RACK1 contributes to the progression of cancer." (PMID 21978545, 2011). "Other mechanisms by which SGs prevent cancer cell resistance to bortezomib might involve the sequestration and inactivation of key apoptotic signaling molecules such as RACK1 or TRAF2, thus preventing the initiation of apoptotic cascades." (PMID 20429927, 2010). "Few studies have detected up-regulation of RACK1 in human cancer specimens." (PMID 18442364, 2008). "Subsequently, we highlight tissue- and cell-type-specific roles of RACK1, with a particular emphasis on the nervous system due to its dependence on localized translation and synaptic plasticity, while also referencing its critical functions in immune cells, cancer, and other contexts." (PMID 41373878, 2025). "Thus, targeting RACK1 in combination with immunotherapy may be a promising strategy for the treatment of cancer." (PMID 38315284, 2024). "Notably, RACK1 may promote the migration and invasion of malignant tumors by mediating the epithelial-mesenchymal transition in LC, the PI3K/Akt pathway in PC, and the AMPK/YAP pathway in CRC." (PMID 37601269, 2023). "Therefore, organ specificity may contribute to the versatile roles of RACK1 in cancer, accounting for the heterogeneity of the pooled results from various cancers." (PMID 37601269, 2023). "RACK1 may, in addition, protect cells from apoptosis in cancer." (PMID 38069262, 2023). "Hence, RACK1 acts as a tumor promoter in these types of cancers." (PMID 37848434, 2023). "Thus, RACK1 is a crucial factor affecting the development of cancer." (PMID 36658304, 2023). "Indeed, RACK1 is aberrantly expressed in several cancer types, including BC." (PMID 33287384, 2020). "Recently, multiple studies indicated that RACK1 was anomalously expressed in various human cancers (e.g., breast, lung, and liver cancers) and might exert either promotive or suppressive effects on cancer." (PMID 30962803, 2019). "However, reports about the function of RACK1 in cancer are inconsistent." (PMID 30962803, 2019). "Interestingly, Rack1 is also involved in the activation of STAT3 in several cancer cells." (PMID 31113450, 2019). "Interestingly, recent studies have shown that Rack1 also confers resistance to cancer." (PMID 31113450, 2019).
cancer (continued). "For example, there are several proteins (e.g., WNT5A, RACK1, SIRT1 and several F-box proteins) whose expression levels appear to correlate with the risk to acquire certain cancers, yet the same proteins have been observed to confer protection against cancers in other paradigms." (PMID 25453033, 2014). "Thus, in cancer, RACK1 becomes a focal point for transformation signaling." (PMID 21978545, 2011). "RACK1 promoted ERK1/2 phosphorylation and mediated multidrug resistance (MDR) cancer cell migration and invasion." (PMID 38190388, 2024). "High RACK1 expression in OSCC cells correlated with increased M2 macrophage infiltration, and promoted cancer progression by increasing the M2/M1 macrophage ratio via the NF-κB pathway." (PMID 37013637, 2023). "Thus, RACK1 may function as a substrate for the UPS in these types of cancer cells." (PMID 37848434, 2023). "Therefore, it may be possible to identify a cancer-specific target from the upstream of RACK1." (PMID 33323973, 2021). "Therefore, EDCs-mediated RACK1 regulation in both contexts could be central to understand the role of endocrine-mediated microenvironment regulation and to link innate immune activation with cancer progression through RACK1." (PMID 33287384, 2020). "In this regard, the scaffold protein Receptor for Activated C Kinase 1 (RACK1) is an EDC target in the immune context and an important molecular player for cancer progression." (PMID 33287384, 2020). "Using siRNA screening, we identified RAB40C as the ubiquitin E3 ligase responsible for ubiquitination of RACK1, and that the action of RAB40C in controlling RACK1 levels is crucial to both cancer cell growth and migration of T cells." (PMID 30112187, 2018). "Phosphorylation of MCM7 mediated by EGFR-p56Lyn and RACK1-Akt promotes MCM complex assembly and chromatin loading, therefore enhancing DNA synthesis and cancer cell proliferation." (PMID 30062004, 2018). "Next, we set out to show that the control of RACK1 levels by RAB40C can have functional consequences in the transformation and proliferation of cancer cells, and in the migration of T cells." (PMID 30112187, 2018). "Our in vitro studies indicated that the interaction between RACK1 and NHE6 contributes to intrinsic Dox resistance in hypoxic cancer cells." (PMID 28635961, 2017). "The interaction between RACK1 and FAK is found at nascent adhesions and is required at the leading edge of polarized cancer cells to sense direction." (PMID 21978545, 2011). "Moreover, the levels of downstream molecules (including p-eIF4E, cyclin D1, snail, and Bcl2) regulated by RACK1 were also decreased after SENP3 knockdown, which is consistent with the impact of SENP3 on cancer hallmarks." (PMID 39755756, 2025). "Even though the receptor for activated C kinase 1 (RACK1) is well recognized as a potential target protein for various cancers, there is still no commercial therapeutic drug available." (PMID 39458945, 2024). "Conversely, the H9 antibody inhibited cancer cell growth in the control group where RACK1 was not silenced." (PMID 39458945, 2024). "Both RACK1 and SFPQ regulate numerous cancer-related cellular processes." (PMID 35552415, 2022). "It has been demonstrated that RACK1 could regulate ANXA2 phosphorylation to make it involved in the invasion and metastasis of drug-resistant carcinoma cells." (PMID 39290334, 2022). "Thus, DKC1125 disorganized the specific cellular context of the KITENIN complex and had a remarkable effect on cancer cells expressing high levels of KITENIN and RACK1." (PMID 34039363, 2021). "LGALS1, NPM1, RACK1, and PERP were upregulated from ductal to cancer cells." (PMID 34326696, 2021). "Cancer-derived variants of BRCA1, BARD1, OLA1, and RACK1 failed to interact, and aberrant expression of these proteins caused centrosome amplification due to centriole overduplication only in mammary tissue-derived cells." (PMID 32722046, 2020).
cancer (continued). "Indeed, RACK1 can favour EDC-mediated pro-inflammatory events in the immune context and, in parallel, promote cancer progression by binding key players necessary for cell proliferation, migration, invasion, metastasization and EMT." (PMID 33287384, 2020). "Knockdown of Rack1 significantly inhibited proliferation and invasion of MDR cancer cells." (PMID 27754360, 2016). "In the absence of RACK1, the H9 antibody treatment did not inhibit cancer cell growth." (PMID 39458945, 2024). "Therefore, we will explore whether OTUB1 affects the function of macrophages and other immune cells through RACK1 in HCC and its potential related mechanisms in our future studies to improve HCC patient outcomes in cancer immunotherapy." (PMID 38315284, 2024). "Subgroup analysis for RACK1 expression and OS was based on cancer type (digestive or non-digestive system cancers) and sample size (sample size ≥ 100 or <100), as well as the source of HRs(reported and estimated) and the Cox analysis method (multivariate and univariate)." (PMID 37601269, 2023). "However, the current study demonstrated decreased RACK1 expression in cancer tissues from the collected 46 CSCC patients compared to normal cervical tissues from 30 cases." (PMID 32792866, 2020). "Likewise, Rack1 has also been reported to regulate EMT and contribute cancer metastasis." (PMID 31113450, 2019). "Our results demonstrated that silencing of NONO reduced the protein levels of eIF4E and RACK1, suggesting that NONO may have a role in regulating the protein translation process in cancer cells." (PMID 37370134, 2023).